CEP120 (centrosomal protein 120)
Description:
Plays a role in the microtubule-dependent coupling of the nucleus and the centrosome. Involved in the processes that regulate centrosome-mediated interkinetic nuclear migration (INM) of neural progenitors and for proper positioning of neurons during brain development. Also implicated in the migration and selfrenewal of neural progenitors. Required for centriole duplication and maturation during mitosis and subsequent ciliogenesis (By similarity). Required for the recruitment of CEP295 to the proximal end of new-born centrioles at the centriolar microtubule wall during early S phase in a PLK4-dependent manner.
Synonyms: CCDC100; FLJ36090; JBTS31; SRTD13
Tractability: PROTAC: ubiquitination databases record sites on it; its protein half-life has been measured.
Gene: Protein-coding gene on chromosome 5 (123,344,890 to 123,423,592, reverse strand). Ensembl gene ENSG00000168944.
Subcellular location: Cytoplasm, cytoskeleton, microtubule organizing center, centrosome
Subcellular location (Human Protein Atlas): Annulus; Flagellar centriole; Microtubules; Cytosol; Mid piece; Mitotic spindle; Perinuclear theca
Gene Ontology:
Molecular function: protein binding
Biological process: positive regulation of centriole elongation; positive regulation of establishment of protein localization; centrosome cycle; interkinetic nuclear migration; positive regulation of centrosome duplication; positive regulation of cilium assembly; positive regulation of cell cycle process; positive regulation of organelle assembly; regulation of centrosome duplication; regulation of protein localization
Cellular component: centriole; centrosome
Genetic constraint (gnomAD): Loss-of-function variants: 70 observed, 91.82 expected, observed/expected ratio (o/e) 0.76, 90% interval 0.63 to 0.93. The upper end of that interval is the gene's LOEUF score, 0.93, which puts it in group 3 of 6, group 1 being the genes least tolerant of losing a copy. Missense variants: 1,020 observed, 981.99 expected, observed/expected ratio (o/e) 1.04, 90% interval 0.99 to 1.09. Synonymous variants: 337 observed, 339.69 expected, observed/expected ratio (o/e) 0.99, 90% interval 0.91 to 1.09.
Gene-disease validity (ClinGen):
ClinGen rates the evidence that CEP120 causes each of these diseases.
ciliopathy (autosomal recessive): Definitive. A genetic disorder of the cellular cilia or the cilia anchoring structures, the basal bodies, or of ciliary function.
Homologues: Orthologues: chimpanzee CEP120 (99% identical), macaque CEP120 (99% identical), pig CEP120 (94% identical), dog CEP120 (93% identical), rabbit CEP120 (91% identical), rat Cep120 (91% identical), mouse Cep120 (90% identical), guinea pig CEP120 (85% identical), tropical clawed frog cep120 (70% identical), zebrafish cep120 (56% identical).
Diseases named in the same sentence as CEP120 in open-access papers:
CEP120 is named in the same sentence as 33 diseases in open-access papers, as found by Europe PMC text mining. Sharing a sentence is not in itself a finding about the gene and the disease. The quoted sentences say what the papers report.
ciliopathy (15 papers, 2015 to 2025). "The patient also carries a single heterozygous variant in the CEP120 gene which is associated with recessive diseases and can confer carrier status for conditions known as ciliopathies." (PMID 38494246, 2024). "Recent studies showed that CEP120 gene mutations cause complex ciliopathy phenotypes in humans, including Joubert syndrome and Jeune asphyxiating thoracic dystrophy, suggesting that CEP120 plays an additional role in ciliogenesis." (PMID 30988386, 2019). "Using X-ray crystallography, we show that the ciliopathy-associated centriolar protein CEP120 contains three C2 domains." (PMID 29847808, 2018). "Altogether, our results suggest a vital role for CEP120 C2B functionality in ciliogenesis while inferring a complex genotype-phenotype relation of the ciliopathy-linked CEP120 alleles." (PMID 29847808, 2018). "More recently, mutations in Cep120 were identified in patients with ciliopathy phenotypes, namely Joubert syndrome and Jeune Asphyxiating Thoracic Dystrophy, further highlighting a critical role in centriole-centrosome-cilia biology." (PMID 29741480, 2018). "In summary, our study elucidates the structural organization of CEP120, its perturbation caused by two ciliopathy-associated mutations in vitro, and the consequences of this perturbation on CEP120 and centriole function in vivo." (PMID 29847808, 2018). "Our results provide insight into the disease mechanism of two ciliopathic mutations in CEP120, identify putative binding partners of CEP120 C2B, and suggest a complex genotype-phenotype relation of the CEP120 ciliopathy alleles." (PMID 29847808, 2018). "Here, we show that a daughter centriole-associated ciliopathy protein, Cep120, plays a critical inhibitory role at daughter centrioles." (PMID 29741480, 2018). "structurally and functionally characterize a conserved C2 domain of the centriolar protein CEP120, which harbors two distinct ciliopathy-associated mutations." (PMID 29847808, 2018). "Mutations in the known genes causative of JS and other ciliopathies were excluded in all patients with CEP120 mutations." (PMID 27208211, 2016). "Our findings broaden the spectrum of phenotypes caused by CEP120 mutations that account for nearly 1% of patients with JS as well as for more complex ciliopathy phenotypes." (PMID 27208211, 2016). "In conclusion, this study adds CEP120 to the growing list of causative genes for a variety of clinically distinct but overlapping ciliopathies." (PMID 27208211, 2016). "The CEP120-associated phenotype ranges from mild classical JS in four patients to more severe conditions in two fetuses, with overlapping features of distinct ciliopathies that include TCDOE, MKS, JATD and OFD syndromes." (PMID 27208211, 2016). "It will be interesting, therefore, to examine the contribution of CEP120, if any, to the mutation burden in these and other related ciliopathies." (PMID 25361962, 2015). "The CEP120 gene has been linked to a broad range of clinical phenotypes from mild Joubert syndrome to severe conditions overlapping with multiple ciliopathies, including Meckel-Gruber syndrome, Jeune asphyxiating thoracic dystrophy, and orofaciodigital syndromes." (PMID 40500351, 2025). "Biallelic mutations in the CEP120 gene were identified in four probands with JS and two fetuses with overlapping ciliopathy phenotypes, all segregating with the disease within the families (three variants were present in homozygous and six in compound heterozygous state)." (PMID 27208211, 2016). "Moreover, Cep120 mutations were recently identified in two ciliopathy syndromes, namely Joubert Syndrome (JS) and Jeune Asphyxiating Thoracic Dystrophy (JATD); patients display multi-organ pathologies including severe congenital renal developmental defects and fibrotic kidney disease." (PMID 38177914, 2024).
ciliopathy (continued). "Thus, as suggested for two closely related ciliopathy mutations in CEP120, the genetic backgrounds of the affected patients might modify the exact clinical manifestation of these ciliopathy mutations instead." (PMID 34499853, 2022). "Our results indicate that Cep120 helps to maintain centrosome homeostasis by inhibiting untimely maturation of the daughter centriole, and defines a potentially new molecular defect underlying the pathogenesis of ciliopathies such as Jeune Asphyxiating Thoracic Dystrophy and Joubert syndrome." (PMID 29741480, 2018). "Conditional deletion of the ciliopathy gene Cep120, which is essential for centrosome duplication, in the stromal mesenchyme resulted in reduced abundance of interstitial lineages including pericytes, fibroblasts and mesangial cells." (PMID 38177914, 2024). "Mutations in ARL3 and CEP120 are rare and relatively new causes of JSRD and other related ciliopathies." (PMID 33297941, 2020). "CEP120 mutations have been shown to cause JSRD and Jeune syndromes, and overlapping ciliopathy phenotypes such as tectocerebellar dysraphia with occipital encephalocele (TCDOE), Meckel syndrome (MKS) and oro-facial-digital (OFD) syndromes." (PMID 33297941, 2020). "Intriguingly, mutations in the CEP120 interactor TALPID3 can give rise to hybrid ciliopathies with JATD- and JS-like features." (PMID 29847808, 2018). "Variations on the CEP120 gene lead to Ciliopathies, which are a group of clinical disorders affecting the primary cilium, a 9 + 0 immobile monocilium, and may involve the mobile monocilium or the 9 + 2 motile cilia." (PMID 38494246, 2024). "We found that the V194A and A199P mutations in CEP120 both impaired normal recruitment of TALPID3 to centriole distal ends, and thus, insufficient centrosomal TALPID3 could contribute to CEP120-linked ciliopathies." (PMID 29847808, 2018). "Furthermore, we identified CEP120 mutations in two fetuses (MKS-2930 and SW-476410) with more complex phenotypes and overlapping features of distinct ciliopathies." (PMID 27208211, 2016). "Co-injection of human CEP120 RNA resulted in partial but significant rescue of the curvature of the tail and hydrocephalus aspects of the morpholino-induced ciliopathy phenotype, however only the tail curvature rescue was still significant after Bonferroni correction." (PMID 25361962, 2015). "Together, our findings reveal a novel role of CEP120 in ciliogenesis by showing that it interacts with C2CD3 and Talpid3 to assemble centriole appendages and by illuminating the molecular mechanism through which the CEP120 (I975S) mutation causes complex ciliopathies." (PMID 30988386, 2019). "We herein showed that CEP120 directly interacts with C2CD3 and Talpid3, making it particularly notable that mutations in all three encoding genes reportedly give rise to a similar spectrum of ciliopathies, including the overlapping clinical features of JS and JATD26,27,50–53." (PMID 30988386, 2019). "Furthermore, this work lays the foundation for future research aimed at obtaining a full mechanistic understanding of the role of CEP120 in ciliogenesis, which will undoubtedly provide vital insight into the disease mechanisms of JS and the devastating ciliopathy JATD." (PMID 29847808, 2018).
Joubert syndrome (10 papers, 2016 to 2025). Joubert syndrome (JS) is characterized by congenital malformation of the brainstem and agenesis or hypoplasia of the cerebellar vermis leading to an abnormal respiratory pattern, nystagmus, hypotonia, ataxia, and delay in achieving motor milestones. "For instance, biallelic variants in CEP120 results in Joubert syndrome 31 and severe short-rib thoracic dysplasia type 13 while spectrum of KIAA0753 related conditions extends to Joubert syndrome 38, orofaciodigital syndrome XV andshort-rib thoracic dysplasia 21without polydactyly." (PMID 38702430, 2024). "In addition, biallelic mutations of the centrosomal protein 120 gene (CEP120), already associated with Joubert syndrome, cause a variety of SRTD, also known as Jeune asphyxiating thoracic dystrophy." (PMID 34356089, 2021). "Many of the genes that are apparently co-regulated with TALPID3 have been associated in some way with regulatory functions of primary cilia, including CEP120 which, like KIAA0596, is mutated in human Joubert syndrome." (PMID 30086717, 2018).
Jeune asphyxiating thoracic dystrophy (9 papers, 2016 to 2025). "We present six probands carrying nine distinct mutations (of which eight are novel) in the CEP120 gene, previously found mutated only in Jeune asphyxiating thoracic dystrophy (JATD)." (PMID 27208211, 2016).
Hydrocephalus (3 papers, 2014 to 2024). Hydrocephalus is an active distension of the ventricular system of the brain resulting from inadequate passage of CSF from its point of production within the cerebral ventricles to its point of absorption into the systemic circulation. "Inactivation of Cep120 in the central nervous system leads to both hydrocephalus, due to the loss of cilia on ependymal cells, and severe cerebellar hypoplasia, due to the failed proliferation of GNPs." (PMID 25251415, 2014). "Inactivation of Cep120 in the central nervous system results in severe hydrocephalus and cerebellar hypoplasia, subsequently causing lethality." (PMID 25251415, 2014). "Conditional deletion of Cep120 in the central nervous system causes hydrocephalus and cerebellar hypoplasia, while siRNA-mediated depletion of Cep120 in the developing mouse brain disrupts growth and self-renewal of the neural progenitor pool during neocortical development." (PMID 38177914, 2024). "Thus, the development of hydrocephalus in the Cep120 mutant is most likely due to the loss of cilia on ependymal cells." (PMID 25251415, 2014). "The result suggests that the lack of motile cilia on ependymal cells is the cause of hydrocephalus in the Cep120 mutant." (PMID 25251415, 2014). "Conditional knockout of Cep120 in the CNS led to hydrocephalus and cerebellar hypoplasia." (PMID 25251415, 2014).
Obesity (2 papers, 2019 to 2021). Accumulation of substantial excess body fat. "For example, the molecular functional mechanisms of CEP120, TSC22D2, Al090771.1 and LHX2 have not been yet linked to obesity, fat distribution and obesity comorbidities." (PMID 34072523, 2021).
COVID-19 (1 paper, 2022). A disease caused by infection with severe acute respiratory syndrome coronavirus 2. "For the suggestive COVID-19 protective signal observed on chromosome 5, the promoter regions of two flanking genes CEP120 and CSNK1G3 were less accessible in the deceased group at hospital admission and follow-up." (PMID 35648852, 2022).
cyst (1 paper, 2024). A sac-like closed membranous structure that may be empty or contain fluid or amorphous material. "How do mutations in Cep120 and other centrosome biogenesis proteins that manifest in the stromal progenitors contribute to the overall renal dysplasia, fibrotic scarring and cyst formation that occurs in NPH, JS, and JATD patients?" (PMID 38177914, 2024).
epilepsy (1 paper, 2025). A brain disorder characterized by episodes of abnormally increased neuronal discharge resulting in transient episodes of sensory or motor neurological dysfunction, or psychic dysfunction. "A male patient with compound heterozygous missense variants in CEP120 presented with ASD, speech delay, epilepsy, dolichocephaly, and hyperprolinemia type I. CEP120 plays a role in centriole biogenesis and cerebellar development; its disruption may underlie the neurological phenotype." (PMID 40558542, 2025).
gastric cancer (1 paper, 2024). A primary or metastatic malignant neoplasm involving the stomach. "CEP120/USP54/PLK4 enhances centrosome amplification and gastric cancer advancement." (PMID 39605891, 2024).
Primary microcephaly (1 paper, 2018). Head circumference below 2 standard deviations below the mean for age and gender at birth. "The absence of a centriole duplication phenotype may also explain why neither JS nor JATD mutations in CEP120 seem to cause primary microcephaly or primordial dwarfism, human disorders associated with mutations in core centriolar proteins." (PMID 29847808, 2018).
Ureteral obstruction (1 paper, 2024). Obstruction of the flow of urine through the ureter. "We performed unilateral ureteral obstruction (UUO) in control and Cep120-KO mice at P60 and collected tissues 7 days post-injury." (PMID 38177914, 2024).
ZTTK syndrome (1 paper, 2025). "In 2/61 cases, RNA-seq revised diagnoses (EPG5 to LZTR1 in an individual with a Noonan syndrome-like disorder) and discovered an additional relevant gene (CEP120 in addition to SON in an individual with ZTTK syndrome)." (PMID 40593860, 2025).
CEP120 also shares sentences with these, for which no sentence is quoted: orofaciodigital syndrome (3 papers); amyotrophic lateral sclerosis (1); Bardet-Biedl syndrome (1); brain malformations (1); Brugada syndrome (1); cancer (1); Cornelia de Lange syndrome (1); hyperprolinemia type 1 (1); Joubert syndrome 31 (1); Joubert syndrome 38 (1); kidney disease (1); Meckel-Gruber syndrome (1); myeloma (1); polydactyly (1); primordial dwarfism (1); renal dysplasia (1); retinal diseases (1); skeletal disease (1); systemic lupus erythematosus (1); Urbach-Wiethe disease (1); Usher syndrome (1).